INS (insulin)
Diseases named in the same sentence as INS in open-access papers (continued):
Sharing a sentence is not in itself a finding about the gene and the disease.
endotoxemia (89 papers, 2004 to 2026). "As a result, bacteremia and endotoxemia ensue that is associated with the initiation of inflammation in peripheral tissues and insulin resistance." (PMID 37181127, 2023). "H. cordata, together with metformin, exerts intensive sensibilization to insulin; the corresponding mechanisms are associated with alleviation of endotoxemia via regulation of gut microbiota, particularly Roseburia, Akkermansia, and Gram-negative bacterium." (PMID 28937612, 2017). "Taken together, these results indicate that insulin hypersensitive PTEN hepatocyte deficient mice are protected in endotoxemia through normal glucose homeostasis and reduced inflammatory cytokine production." (PMID 23825606, 2013). "In human study participants, experimental endotoxemia, which produces an insulin-resistant state, causes a dramatic rise in circulating resistin levels." (PMID 15578112, 2004). "The specific deletion of this receptor in mice results in a small number of M1 and enhanced insulin sensitivity, however, more research is needed to understand the complete mechanisms driving M1 polarization in AT during endotoxemia and associated diseases in dairy cows." (PMID 38581064, 2024). "Bacterial-derived toxins cause endotoxemia by promoting inflammatory processes and immune cell infiltration in different organs and systems while impacting metabolic function by altering lipolysis, mitochondrial activity, and insulin sensitivity." (PMID 38581064, 2024). "The physiological meaning of this increased relaxation requires further investigation, but, since endotoxemia is associated with insulin resistance in several tissues, it may serve to increase glucose supply into the tissues." (PMID 35795581, 2022). "Extended periods of endotoxemia are characterized by a reduction of glucose utilization associated with nonoxidative glucose disposal impairment as well as increased levels of glucose and growth hormones, which are known for their insulin-antagonistic effects." (PMID 32295104, 2020). "Endotoxemia-induced low-grade inflammation can cause a decrease in insulin sensitivity." (PMID 32064276, 2020). "This increase in serum LPS levels has the potential to cause endotoxemia and low-grade inflammation, which could, in turn, decrease insulin sensitivity." (PMID 32064276, 2020). "Interestingly, early endotoxemia in the setting of infection has been associated with increased insulin sensitivity related to increased glucose uptake in the muscle, contributing to observed hypoglycemia in early sepsis." (PMID 32295104, 2020). "Notably, when studied individually, endotoxemia and hypothermia are generally associated with reduced insulin function." (PMID 28706520, 2017). "Since circulating LPS concentrations are reported to be in the ng/mL range in endotoxemia associated with metabolic diseases, our results suggest that LPS inhibition of insulin gene expression might occur in vivo in humans." (PMID 22558381, 2012). "In addition, based on the results of the present study, it should be noted that, during the LD period in sheep with acute endotoxemia, the additional i.v. administration of leptin caused the increase in insulin concentration to be more gradual and spread over time." (PMID 35897684, 2022). "Hence, nutrient excess, endotoxemia and the associated pro-inflammatory cytokines have deleterious effect on both insulin sensitivity and beta-cell function, which may contribute to the etiology of T2D." (PMID 25383781, 2014). "Elevated LPS has been shown to provoke metabolic endotoxemia, which in turn has been demonstrated to drive low-grade inflammation, insulin resistance, and adiposity." (PMID 41459155, 2025). "Interesting and significant differences between the study groups were also observed regarding the effects on gonadotropins, insulin, lipids, and markers of endotoxemia." (PMID 39636391, 2025). "For instance, endotoxemia is known to stimulate lipolysis and impair insulin sensitivity in adipocytes." (PMID 40583106, 2025).
endotoxemia (continued). "Weight-loss interventions and specific dietary patterns—notably Mediterranean-style diets—consistently lower these endotoxemia markers in parallel with improvements in insulin sensitivity." (PMID 40871736, 2025). "It showed that a reduction in pancreatic insulin secretion existed with an inflammatory liver produced by mild portal endotoxemia." (PMID 39997251, 2025). "Secondary outcomes included serum lipoprotein particle profiles, neutrophil NADPH oxidase activity, serum inflammatory markers Glyc-A and IL-6, biomarkers of endotoxemia, plasma glucose, and serum insulin and NEFA." (PMID 38380649, 2024). "Anti-inflammatory properties that improve gut health reduce endotoxemia and enhance insulin sensitivity." (PMID 39429422, 2024). "Endotoxemia stimulates miR-155 expression in pancreatic β-cells, which increases insulin secretion by targeting V-maf musculoaponeurotic fibrosarcoma oncogene family protein B (Mafb) under hyperlipidemic conditions." (PMID 38812051, 2024). "The study reveals that exercise training for a short duration significantly reduces intestinal inflammation, decreases endotoxemia, and induces favorable alterations in gut microbiota profiles in insulin-resistant individuals." (PMID 38646363, 2024). "SCFAs increase insulin signaling and insulin sensitivity with their curative effects on systemic inflammation and endotoxemia by decreasing intestinal permeability." (PMID 37009872, 2023). "Previous studies have demonstrated that a high-fat diet induces intestinal inflammation, enhanced intestinal permeability, and endotoxemia that induces systemic insulin resistance." (PMID 37373776, 2023). "First, it was shown that CLCX10 is released abundantly by the adipose tissue in response to an acute inflammatory response induced by endotoxemia, thereby leading to insulin resistance under stress conditions." (PMID 36059840, 2022). "SCFAs have been shown to improve systemic inflammation via reducing intestinal permeability and endotoxemia demonstrated to impair insulin signaling and insulin sensitivity." (PMID 35565691, 2022). "We also studied the effect of kale in attenuating endotoxemia because it is related to both inflammation and insulin resistance." (PMID 34432833, 2021). "Researchers in Alexandria, Egypt studied endotoxemia in obese children and adolescents and its possible relationship with insulin, lipid profile and C-reactive protein." (PMID 33924229, 2021). "Meanwhile, Verrucomicrobia has been recently proposed as a hallmark of a healthy gut due to its anti-inflammatory and immunostimulant properties and its ability to improve gut barrier function, insulin sensitivity, and endotoxemia." (PMID 34007853, 2021). "Previous research showed a detrimental role of bacterial LPS translocation (termed endotoxemia) on insulin sensitivity by activating Toll-like receptors 4 (TLR4) and triggering the secretion of proinflammatory cytokines." (PMID 34361925, 2021). "We report on effects of the vegetable on body weight, fat accumulation in the liver and adipose tissue, systemic insulin resistance, endotoxemia and the expression of genes involved in adipogenesis, lipogenesis and inflammation in adipose tissue." (PMID 34432833, 2021). "We elucidated the in vivo immune modulatory effects of insulin using a GIK solution administered to a LPS induced murine endotoxemia model." (PMID 33679687, 2020). "This is interesting because Akkermansia muciniphila has anti-inflammatory and immunostimulant properties and can improve gut barrier function, endotoxemia, and insulin sensitivity." (PMID 32937846, 2020). "The levels of TNF-α and IL-6 were also inhibited by insulin treatment in a LPS induced murine endotoxemia model." (PMID 33679687, 2020). "This microorganism has been proposed by others as a hallmark of a healthy gut due to its anti-inflammatory and immunostimulant properties and its ability to improve gut barrier function, insulin sensitivity and endotoxemia." (PMID 31164869, 2019).
endotoxemia (continued). "This microorganism, also found in the Chilean population, has been proposed as a hallmark of a healthy gut due to its anti-inflammatory and immunostimulant properties and its ability to improve gut barrier function, insulin sensitivity and endotoxemia." (PMID 31164869, 2019). "It has been reported that endotoxemia negatively correlates with Bifidobacterium and positively correlates with improved glucose tolerance, glucose-induced insulin secretion, decreased endotoxemia, and adipose tissue proinflammatory cytokines." (PMID 30837966, 2019). "Increased glucose in endotoxemia or other hypermetabolic states is directly attributed to tissue insulin resistance and endocrine derangement and reflects more severely disrupted homeostatic mechanisms." (PMID 25237781, 2014). "When combined with glucose infusion, however, endotoxemia dramatically impairs glucose disposal due to marked insulin resistance." (PMID 23826335, 2013). "To investigate vasculo-protective effects of insulin-sensitivity in murine endotoxemia, we analyzed the expression and the release/shedding of E-selectin/CD62E in challenged animals." (PMID 23825606, 2013). "Herein, using both in vivo and in vitro models of endotoxemia we delineated the important role that iNOS-dependent tyrosine nitration of the proximal insulin signaling intermediate, IRS-1, plays in endotoxemia-induced skeletal muscle IR." (PMID 21206533, 2010). "The inhibition of IDO activity could improve insulin sensitivity, maintain the intestinal mucosal barrier, reduce endotoxemia and chronic inflammation, and regulate lipid metabolism in both liver and adipose tissues." (PMID 35721725, 2022). "Miller at al. in a study of 192 participants observed positive associations between endotoxemia levels and total cholesterol, serum TGs, and insulin, while they found a negative association between endotoxemia and HDL-C." (PMID 34436472, 2021). "Previous studies have found that the gut microbiota could decrease insulin sensitivity by endotoxemia and low-grade inflammation." (PMID 32064276, 2020). "As periodontal bacterial species are significant sources of endotoxemia and may directly stimulate insulin secretion, we hypothesized that increased bacterial virulence may exert an adverse effect on rat pancreatic β-cell function via PI3K/AKT signaling." (PMID 30039349, 2019). "Recently, we have demonstrated that orally administered Porphyromonas gingivalis, a representative periodontopathic bacterium, induces endotoxemia via reduced gut barrier function coupled with changes in gut microbiota composition, resulting in systemic inflammation and insulin resistance." (PMID 27576340, 2016). "Experiments in rats suggest that visceral adipose tissue is less responsive to endotoxemia than subcutaneous adipose tissue while human studies have found that visceral adipose tissue is more responsive to epinephrine and less responsive to insulin than subcutaneous adipose tissue." (PMID 27627109, 2016). "In conclusion, suppression of vagal tone and sympathetic predominance during endotoxemia are linked to anti-inflammatory processes and lipid oxidation but not to insulin resistance, while weaker HRV changes in relation to the GLP-1 response are noted during oral fat load." (PMID 25893426, 2015). "Collectively, these data position intestinal barrier integrity as a proximal node linking fermented-food matrices to reduced endotoxemia (LPS/LBP), dampened hepatic TLR4–MyD88–NF-κB signaling, and improved insulin sensitivity." (PMID 41599407, 2026). "Circulating reactive oxygen species (estimated using a neutrophil oxidative burst assay), glucose, insulin, NEFA, lipoprotein particle profiles, inflammatory markers (glycoprotein acetylation (Glyc-A) and IL-6), and biomarkers of endotoxemia were measured." (PMID 38380649, 2024). "Insulin has anti-inflammatory effects, and the application of insulin can reduce pro-inflammatory mediators, especially TNFα and IL6, in animal models of endotoxemia." (PMID 37063831, 2023).
endotoxemia (continued). "Additionally, mice previously submitted to multiple acute endotoxemia had a worsened metabolic profile after the high-fat diet period, showing increased leptin and insulin levels, with impaired glucose homeostasis, as measured by glucose and insulin tolerance tests." (PMID 35335996, 2022). "As a result, HFD -induced endotoxemia and inflammation of adipose tissue was ameliorated by BFT, leading to improved insulin sensitivity and glucose tolerance." (PMID 32218475, 2020). "Endotoxemia and TLR4 signaling control the production of proinflammatory cytokines in target tissues and lead to chronic inflammation and insulin resistance in fat mice." (PMID 32685087, 2020). "Moreover, animals under endotoxemia also develop an increase in glucocorticoid production that precedes that of insulin; thus the enhanced glucocorticoid endogenous environment could be cooperating for maintaining glucose homeostasis, a phenomenon vital for survival during endotoxic shock." (PMID 27347514, 2015). "Endotoxemia can induce P300 via XBP1s in the ER stress pathway in the liver and elevated P300 can disrupt insulin signaling by acetylating IRS1 and 2 in the insulin signaling pathway." (PMID 36836874, 2023). "Interestingly, several reports showed that insulin, a very potent activator of PI3K, significantly reduces the severity of endotoxemia in rodents injected with LPS." (PMID 24740015, 2014). "In summary, we present a low dose human endotoxemia model of inflammation which induces adipose tissue inflammation and systemic insulin resistance in the absence of overt clinical response." (PMID 22709547, 2012). "No increase in endotoxemia nor in systemic inflammation was observed, which could have helped to explain the role the intestinal microbiota plays in the decrease in insulin sensitivity." (PMID 33102570, 2020). "Consequently, metabolic endotoxemia—persistently elevated circulating LPS levels—activates Toll-like receptor-4 (TLR4), an immune receptor that recognizes endotoxins, triggering NF-κB inflammation, signaling, and downstream inflammatory cascades, fostering systemic insulin resistance." (PMID 40871736, 2025). "However, in our study, the effect of the intestinal microbiota on insulin sensitivity could not be explained by an increase in endotoxemia and inflammation as postulated from a mice study." (PMID 33102570, 2020). "Third, alteration of insulin secretion and sensitivity induced by LPS systemic infusion was not affected by ASK1 deletion, suggesting that ASK1 is not involved in the glucoregulatory responses to endotoxemia." (PMID 25383781, 2014).
liver cancer (89 papers, 2012 to 2026). An epithelial or non-epithelial malignant neoplasm that arises from the liver. "Nevertheless, the combination of metformin with insulin or sulfonylureas has been linked to an increased risk of liver cancer in these individuals." (PMID 39949980, 2025). "While sodium–glucose cotransporter-2 inhibitors (SGLT2 inhibitors) have been associated with reduced cancer risk, insulin and SUs have been linked to increased risks of overall, pancreatic, and liver cancers." (PMID 41300987, 2025). "AKR1B10 is upregulated by EGF and insulin through AP-1 signaling and is associated with the development of liver cancer." (PMID 39001490, 2024). "Numerous studies have shown that high levels of insulin, especially in patients with IR, are significantly associated with an increased risk of various tumours, including liver cancer." (PMID 37328795, 2023). "HepG2 cells derived from human liver cancer tissues exhibit biological activities similar to those of normal hepatocytes and are extensively used in insulin resistance studies because exposure to insulin causes cellular damage." (PMID 37754257, 2023). "Subgroup analyses revealed that the positive association between insulin use and liver cancer was restricted to studies conducted in populations from Western regions (n = 4; RR = 2.48, 95% CI = 1.31–4.70)." (PMID 37481610, 2023). "In conclusion, this study found little support for a link between c-peptide, a marker of endogenous insulin release, and most cancers-of-interest with the notable exception of a strong positive association with liver cancer risk." (PMID 36712480, 2022). "The risk of liver cancer in T2DM insulin users was higher than in the general population (IRR = 5.06, 95% CI 3.24, 7.90); the excess risk was similar when comparing those using insulin alone with those treated with diet alone (IRR = 4.52, 95% CI 1.89, 10.82)." (PMID 35681699, 2022). "The conformational change in SORBS1 following insulin stimulation reportedly causes it to interact with the c-Abl oncoprotein to play a role in the insulin signaling pathway of the human liver cancer cell line Hep3B." (PMID 35196185, 2022). "PYCR1 has been reported to be associated with the insulin signalling pathway and to inhibit cell proliferation in liver cancer cells." (PMID 36088469, 2022). "We should consider both viral- and drug-related factors in liver cancer screening programs because chronic viral hepatitis signifies the association between certain insulin analogues and HCC oncogenesis." (PMID 31200528, 2019). "Although insulin is known to regulate glucose metabolism and closely associate with liver cancer, the molecular mechanisms still remain to be elucidated." (PMID 24895527, 2014). "For site-specific cancers, we found that use of insulin was only significantly associated with a higher risk of liver cancer after full adjustment." (PMID 23308218, 2013). "Patients receiving insulin or sulphonylureas had a higher risk of colorectal and liver cancers compared to those receiving metformin after adjusting sex and age." (PMID 22719752, 2012). "Compared to those treated with sulphonylureas or insulin, diabetic patients treated with metformin had a significantly lower risk of developing colorectal and liver cancers." (PMID 22719752, 2012). "Metformin treatment was associated with a decreased risk of colon and liver cancer compared to sulphonylureas or insulin treatment." (PMID 22719752, 2012). "Moreover, the combinations of insulin with metformin and metformin with sulfonylureas were associated with an increased risk of liver cancer in patients with MAFLD and MASLD." (PMID 39949980, 2025). "The medicine may diminish inflammatory cytokine cascades (e.g., TNF-α, IL-6) by reducing glucose levels and enhancing insulin sensitivity, so mitigating liver damage and fibrosis, which elevate the risk of liver cancer." (PMID 40439888, 2025).